CTSL (cathepsin L)
Diseases named in the same sentence as CTSL in open-access papers (continued):
Sharing a sentence is not in itself a finding about the gene and the disease.
depression (1 paper, 2024). "The discovery and validation of TRPV2, ZNF713, and CTSL as potential biomarkers offer a promising avenue for enhancing the precision of depression diagnosis and advancing our understanding of this complex disorder." (PMID 40226717, 2024). "Our findings indicate reduced CTSL expression in patients with MDD, which could impair immune function and contribute to depression." (PMID 40226717, 2024).
female sterility (1 paper, 2014). "Ablation of the cathepsin L gene has been shown to result in female sterility." (PMID 25173815, 2014).
gingival overgrowth (1 paper, 2019). Excessive growth of the gingiva either by an increase in the size of the constituent cells (gingival hypertrophy) or by an increase in their number (gingival hyperplasia). "Complete loss of cathepsin-L function resulted in the development of gingival overgrowth in these patients." (PMID 31320815, 2019).
Granuloma (1 paper, 2024). A compact, organized collection of mature mononuclear phagocytes, which may be but is not necessarily accompanied by accessory features such as necrosis. "CTSL is a lysosomal protease that is actively secreted in inflammatory processes, and based on limited mouse models of sarcoidosis, it may affect granuloma formation." (PMID 39316441, 2024).
Hyperammonemia (1 paper, 2026). An increased concentration of ammonia in the blood. "We found that hyperammonemia induces lysosomal dysfunction, with reduced LysoTracker staining and cathepsin L levels and increased LAMP2 content." (PMID 41601700, 2026).
Hyperglycemia (1 paper, 2024). An increased concentration of glucose in the blood. "Our findings underscore the pivotal role of hyperglycemia-induced CTSL maturation in diabetic comorbidities and complications." (PMID 39150053, 2024). "Taking all these factors into consideration, we have ultimately chosen to utilize the hepatoma cell line to investigate how hyperglycemia induces CTSL maturation and subsequently promotes SARS-CoV-2 infection." (PMID 39150053, 2024). "Mechanistically, we proposed that hyperglycemia promoted CTSL maturation by accelerating its translocation from the ER to lysosome via Golgi apparatus." (PMID 39150053, 2024). "In conclusion, our study demonstrates that hyperglycemia drives the maturation and activation of CTSL, for only mature form of CTSL gains its function of proteolysis." (PMID 39150053, 2024). "Chronic hyperglycemia correlates positively with CTSL concentration and activity in diabetic patients, while acute hyperglycemia augments CTSL activity in healthy individuals." (PMID 39150053, 2024). "(h) Proposed mechanisms of hyperglycemia drives CTSL maturation and enhances SARS-CoV-2 infection." (PMID 39150053, 2024). "In summary, acute hyperglycemia specifically elevates CTSL activity, while chronic hyperglycemia may impact both CTSL activity and concentration." (PMID 39150053, 2024). "Therefore, chronic hyperglycemia is strongly associated with both CTSL concentration and activity, while acute hyperglycemia only affects CTSL activity." (PMID 39150053, 2024). "Given that hyperglycemia increased CTSL levels and facilitated SARS-CoV-2 entry into host cells, we hypothesized that high blood glucose promoted SARS-CoV-2 infection through CTSL." (PMID 39150053, 2024).
hypopharyngeal carcinoma (1 paper, 2025). Carcinoma, predominantly squamous cell, arising from the epithelial cells of the hypopharynx. "Together, these findings suggest that USP20 and CTSL are closely linked to metastatic progression and poor clinical outcomes in hypopharyngeal carcinoma, highlighting their potential as prognostic biomarkers and therapeutic targets." (PMID 41261048, 2025). "Correlation analysis revealed a strong positive relationship between USP20 and CTSL expression in hypopharyngeal carcinoma samples (R = .62, p = .0012)." (PMID 41261048, 2025). "Compared with non‐metastatic tumours, metastatic hypopharyngeal carcinoma tissues exhibited significantly higher levels of USP20 and CTSL, accompanied by elevated N‐cadherin and decreased E‐cadherin expression, indicative of an enhanced EMT phenotype." (PMID 41261048, 2025).
IgA nephropathy (1 paper, 2019). "In our study, we found significantly more cathepsin L protein in the glomeruli of patients with MCD, lupus nephritis, and IgA nephropathy." (PMID 30350425, 2019).
Immunodeficiency (1 paper, 2015). Failure of the immune system to protect the body adequately from infection, due to the absence or insufficiency of some component process or substance. "Unsurprisingly, mice deficient in cathepsin L were protected from EAE presumably owing to the previously-described thymic immunodeficiency." (PMID 26075905, 2015).
infarction (1 paper, 2013). A localised pathological necrosis of tissue resulting from obstruction of the blood supply usually by a thrombus, an embolus, or vascular torsion. "Cathepsin L has been shown to participate in the remodelling of various tissues, including post-infarction cardiac tissue." (PMID 24170975, 2013).
keloid (1 paper, 2022). An irregularly shaped, elevated mark on the skin caused by deposits of excessive amounts of collagen during wound healing. "Furthermore, two modules of macrophages (Module2: highly expresses RNASE1, C1QA, CD163, CD14, C1QC, FCGRT, and MS4A7; Module10: highly expresses APOC1, CTSB, CTSL, and TYROBP), which exhibited the characteristics of TAMs, increased significantly in keloid." (PMID 35990663, 2022).
laminopathy (1 paper, 2022). A rare genetic disorder caused by mutations in genes encoding proteins of the nuclear lamina. "Our research identifies cathepsin L as a newly identified lamin B1 protease and mediator of laminopathy observed in AD." (PMID 34905652, 2022).
leishmaniasis (1 paper, 2019). Infectious disease that is transmitted through the bite of hematophagous female phlebotomine sand flies. "Cathepsin L (CTSL) has been proved to help contain leishmaniasis and mycoplasma infection in mice by supporting cellular immune responses, but the regulatory functions of CTSL on mucosal immune responses haven’t been tested and remain undefined." (PMID 30986254, 2019).
leukemia (1 paper, 2012). A malignant (clonal) hematologic disorder, involving hematopoietic stem cells and characterized by the presence of primitive or atypical myeloid or lymphoid cells in the bone marrow and the blood. "We thus concluded, in accordance with previously reported in vivo kinetics, that Atrogin-1, MuRF1, LC3 and Cathepsin L are valuable early markers of muscle atrophy in this mouse model of leukemia." (PMID 22761662, 2012).
limb ischemia (1 paper, 2014). A ischemia that involves the limb. "In the present study, we showed that the early significant increase in kinase signaling is substantially lost after ten days of repeated limb ischemia, and there is up-regulation of the expression of LC3-II and cathepsin L (a lysosomal cysteine protease involved in autophagy signaling)." (PMID 25347774, 2014).
liver cirrhosis (1 paper, 2014). "CTSL expression was significantly correlated with liver cirrhosis, stage, Recurrence and tumor differentiation." (PMID 25384089, 2014). "Additionally, we have shown that CTSL expression was correlated with liver cirrhosis, stage, Recurrence and tumor differentiation." (PMID 25384089, 2014). "These factors include CTSL expression, gender, age, tumor size, Serum HBsAg, serum AFP, tumor size, liver cirrhosis, stage, tumor recurrence and tumor differentiation." (PMID 25384089, 2014).
lung disease (1 paper, 2016). "Although it cannot be concluded that the same is necessarily true in humans, no lung disease associated with mutations in the cathepsin L gene has been observed so far." (PMID 27031696, 2016). "We show here that, like some other proteins of the lysosomal membrane, ABCA3 is a substrate of cathepsin L. Therefore, cathepsin L may represent a potential target to therapeutically influence ABCA3 activity in ABCA3-associated lung disease." (PMID 27031696, 2016). "Interfering with the activity of cathepsin L in alveolar epithelial type II cells may thus represent an approach to ameliorate ABCA3 function in patients suffering from lung disease due to ABCA3 haploinsufficiency." (PMID 27031696, 2016).
lymph node metastasis (1 paper, 2025). "Analysis of TCGA datasets showed that the expression of USP20 and CTSL progressively increased with the extent of lymph node metastasis (N stage), further supporting their association with metastatic potential." (PMID 41261048, 2025).
malignant glioma (1 paper, 2023). A grade III or grade IV glioma arising from the central nervous system. "Cathepsin L is known to play an important role in malignant gliomas." (PMID 37174113, 2023).
meningioma (1 paper, 2010). A generally slow growing tumor attached to the dura mater. "In the present study, we focused on expression of the MIB-1 antigen, PR, cathepsin B and cathepsin L on meningioma cells." (PMID 22933900, 2010). "A larger multivariate study on a larger population is needed to confirm the prognostic value of MIB-1 antigen, PR, cathepsin B and cathepsin L on meningioma cells." (PMID 22933900, 2010). "IH intensity scores for cathepsin B (p=0.007) and cathepsin L (p<0.001) were both higher in the recurrent than in the non-recurrent meningioma group." (PMID 22933900, 2010). "The MIB-1 antigen, cathepsin B and cathepsin L are shown to be expressed more on cells of recurrent meningiomas compared to non-recurrent ones." (PMID 22933900, 2010). "Immunohistochemical intensity scores for cathepsin B (p= 0.007) and cathepsin L (p<0.001) were both higher in the recurrent than in the non-recurrent meningioma group." (PMID 22933900, 2010). "In our series of 54 meningiomas, treated in a single institution, we showed that MIB-1 antigen, cathepsin B and cathepsin L were expressed more in recurrent compared to non-recurrent meningiomas." (PMID 22933900, 2010).
metabolic dysfunction-associated steatohepatitis (1 paper, 2025). Metabolic dysfunction-associated steatohepatitis (MASH, formerly known as nonalcoholic steatohepatitis or NASH) is a type of fatty liver disease. "Interestingly, the sialin-CtsL-Nrf2 pathway is downregulated in human macrophages from metabolic dysfunction-associated steatohepatitis (MASH) patients." (PMID 41034188, 2025).
metastatic melanoma (1 paper, 2010). A melanoma that has spread from its primary site to another anatomic site. "Synthetic cysteinyl proteinase cathepsin B inhibitor CA-074, but not synthetic aspartyl proteinase cathepsin D inhibitor Pepstatin A and cathepsin L inhibitor, significantly reduced the percentage of invading cells (two representative cell lines from primary and metastatic melanoma are shown)." (PMID 20684763, 2010).
Middle East respiratory syndrome (1 paper, 2021). A viral respiratory infection that is caused by the MERS coronavirus (MERS-CoV), which most often manifests with moderate to severe respiratory symptoms, including productive cough and shortness of breath, which can progress to pneumonia and acute respiratory distress syndrome. "CTSL is also known to be associated with Middle East Respiratory Syndrome and bacterial infections in CF airways." (PMID 34442377, 2021).
mycobacterial infection (1 paper, 2020). "The profiles of immune response proteins relevant for mycobacterial infection showed that LTA4H and cathepsin L1 levels increased in response to vaccination or vaccination and infection." (PMID 32344637, 2020).
mycoplasma infection (1 paper, 2019). "These alignment data suggest that pig is an ideal animal model to study the roles of CTSL in immune responses to mycoplasma infection instead of mice." (PMID 30986254, 2019).
myeloma (1 paper, 2020). "Additionally, latent heparanase is activated when it is cleaved by cathepsin L and studies of murine myeloma have shown that reduction in cathepsin L levels greatly reduces tumorigenesis and growth in mice, a potential link with loss of heparanase activation." (PMID 32899927, 2020).
non-Hodgkin lymphoma (1 paper, 2024). Distinct from Hodgkin lymphoma both morphologically and biologically, non-Hodgkin lymphoma (NHL) is characterized by the absence of Reed-Sternberg cells, can occur at any age, and usually presents as a localized or generalized lymphadenopathy associated with fever and weight loss. "We identified associations for variants enriched in African ancestry, many in diseases that lack precise biomarkers, including cis-pQTLs for cathepsin L (CTSL) and Siglec-9, which were linked with sarcoidosis and non-Hodgkin’s lymphoma, respectively." (PMID 39316441, 2024).
ocular hypertension (1 paper, 2017). Abnormally high intraocular pressure. "If α and CTSL both increase with age, a more rapid increase in α relative to CTSL may lead to unstable IOPs and ocular hypertension." (PMID 29261696, 2017).
pancreatic islet cancer (1 paper, 2022). "While there is no information available on the role of CTSL in apoptosis in HCC, mice with pancreatic islet cancer with a knockout in CTSL demonstrated a 337% increase in apoptosis." (PMID 36289617, 2022).
parasite (1 paper, 2020). "Here, the significantly upregulated expression of cathepsin L (6.38 fold) and cathepsin D (15.49 fold) in the infected bryozoans suggested an increased probability of reducing parasite infection in bryozoans." (PMID 32824626, 2020).
prostate adenocarcinoma (1 paper, 2013). "Epithelial cell adhesion molecule (EpCAM) and cathepsin L (CTSL) are epithelial proteins that have been found abundantly expressed in prostate adenocarcinomas." (PMID 24289299, 2013). "Although previous studies suggested an increase in CTSL mRNA expression in prostate adenocarcinomas, a recent study showed that CTSL staining in prostate tissues is comparable between prostate adenocarcinomas and normal tissues." (PMID 24289299, 2013).
Rb (1 paper, 2022). "Immunofluorescence analysis of FFPE specimens of Rb tumors detected strong ZEB1 and cathepsin L positivity in advanced Rb tumor tissues compared with non-advanced Rb." (PMID 36291907, 2022). "However, ZEB1 (FC = 77.2, p < 0.05), SNAI2 (FC = 3.32, p < 0.05), ABCB1 (FC = 4.4, p < 0.05), and CTSL (FC = −3.8, p < 0.05) expressions were significantly downregulated in non-advanced Rb tumors." (PMID 36291907, 2022).
renal carcinoma (1 paper, 2022). A carcinoma arising from the epithelium of the renal parenchyma or the renal pelvis. "On the other hand, high CTSL expression significantly correlated with a long OS in renal cancer patients (p<0.001)." (PMID 35414771, 2022).
renal fibrosis (1 paper, 2025). A final common manifestation of a wide variety of chronic kidney diseases characterized by glomerulosclerosis and tubulointerstitial fibrosis. "This study identifies host cysteine proteases—particularly cathepsin L and caspase-1—as unrecognized drivers of CAUTI pathogenesis and renal fibrosis." (PMID 40980878, 2025).
Respiratory tract infection (1 paper, 2019). An infection of the upper or lower respiratory tract. "Taking into account that CTSL is involved in MHC II–dependent immune responses, we hypothesized that CTSL may provide protection against respiratory tract infections of bacterial pathogens by improving mucosal immunity." (PMID 30986254, 2019).
retinal degeneration (1 paper, 2018). Degeneration of the retina. "While studies are few, inhibition of Cathepsin L also preserves other light‐sensitive cells including the photoreceptors in norpA mutant Drosophila melanogaster that experience light‐dependent retinal degeneration." (PMID 29692003, 2018).
sarcoidosis (1 paper, 2024). Sarcoidosis is a multisystemic disorder of unknown cause characterized by the formation of immune granulomas in involved organs. "We also found associations for relatively rare diseases that lack precise biomarkers, including a cis-pQTL for cathepsin L (CTSL) associated with sarcoidosis, highlighting the value of proteogenomic studies and PheWAS in uncovering potential novel biology for less common phenotypes." (PMID 39316441, 2024). "We found a cis-pQTL in CTSL, rare in individuals of NFE ancestry, to be associated with sarcoidosis in the Black-only analysis." (PMID 39316441, 2024). "Further studies are needed to assess the role of CTSL both in the pathogenesis and as a biomarker of sarcoidosis in diverse human cohorts." (PMID 39316441, 2024).
serous ovarian carcinomas (1 paper, 2014). "It has been reported that CSTB, derived from serous ovarian carcinomas, strongly inhibits papain and cathepsin L and moderately inhibits cathepsin B." (PMID 24452274, 2014).
Skeletal muscle atrophy (1 paper, 2024). The presence of skeletal muscular atrophy (which is also known as amyotrophy). "Their target genes, including FBXO32 (also known as MAFbx/Atrogin-1), TRIM63 (also known as MuRF1), CTSL, and BNIP3, are commonly upregulated in various models of skeletal muscle atrophy, and their upregulation accelerates protein degradation." (PMID 38540418, 2024).
Skin Cutaneous Melanoma (1 paper, 2022). "The results revealed that, all types of cancer tissues showed CTSL expression; the highest levels were found in SKCM (Skin Cutaneous Melanoma)." (PMID 35414771, 2022).
systemic sclerosis (1 paper, 2018). A chronic disorder, possibly autoimmune, marked by excessive production of collagen which results in hardening and thickening of body tissues. "In contrast to ERG, the function of FLI1 is less-characterized in ECs; its ablation results in upregulation of CTSL and CXCL6 and downregulation of CXCL5 and CCN1 in the context of systemic sclerosis." (PMID 30500808, 2018).
testicular tumors (1 paper, 2022). "Similarly, higher levels of cathepsin L were reported in kidney and testicular tumors and in most cancers of the breast, ovary, colon, adrenal, bladder, prostate, and thyroid." (PMID 36364419, 2022).
type 1 diabetes (1 paper, 2024). "They suggested that cathepsin-L may be a new target molecule that can be used in the treatment of type 1 diabetes." (PMID 38775500, 2024).
Ureteral obstruction (1 paper, 2020). Obstruction of the flow of urine through the ureter. "Interestingly, using a model of unilateral ureteral obstruction, the authors found that CTSB or CTSL deficiency in mice exacerbates kidney fibrosis, whereas CTSS or CTSK deficiency protects it." (PMID 33379277, 2020).
uveal melanoma (1 paper, 2022). A melanoma derived from melanocytes of the uveal tract. "However, there was a negative association between CTSL and the infiltrating immune cells in uveal melanoma." (PMID 35155389, 2022).
Ventricular arrhythmia (1 paper, 2015). "We have previously demonstrated that even in the absence of a host systemic inflammatory/immune response to the parasite, ventricular arrhythmias can be induced by Lister 427 trypanosomes ex vivo due to the effect of a secreted/excreted protease, T. brucei cathepsin-L (TbCatL), on cardiomyocytes." (PMID 26023927, 2015).